LSM7 (LSM7 homolog, U6 small nuclear RNA and mRNA degradation associated)
Description:
Plays a role in pre-mRNA splicing as component of the U4/U6-U5 tri-snRNP complex that is involved in spliceosome assembly, and as component of the precatalytic spliceosome (spliceosome B complex). The heptameric LSM2-8 complex binds specifically to the 3'-terminal U-tract of U6 snRNA.
Synonyms: YNL147W; LDCA
Tractability: Small molecule: a structure with a bound ligand is known. PROTAC: ubiquitination databases record sites on it; its protein half-life has been measured.
Gene: Protein-coding gene on chromosome 19 (2,321,520 to 2,328,612, reverse strand). Ensembl gene ENSG00000130332.
Subcellular location: Nucleus
Subcellular location (Human Protein Atlas): Nucleoli fibrillar center
Pathways (Reactome):
Metabolism of RNA: mRNA Splicing - Major Pathway; mRNA decay by 5' to 3' exoribonuclease
Gene Ontology:
Molecular function: protein binding; RNA binding; U6 snRNA binding
Biological process: mRNA splicing, via spliceosome; deadenylation-dependent decapping of nuclear-transcribed mRNA; spliceosomal snRNP assembly; spliceosomal tri-snRNP complex assembly; nuclear-transcribed mRNA catabolic process
Cellular component: cytoplasm; Lsm2-8 complex; nucleus; precatalytic spliceosome; spliceosomal complex; U2-type precatalytic spliceosome; U4/U6 x U5 tri-snRNP complex; catalytic step 2 spliceosome; cytosol; Lsm1-7-Pat1 complex; nucleoplasm; spliceosomal tri-snRNP complex; U12-type spliceosomal complex; U2-type prespliceosome; U4/U6 snRNP; U4atac/U6atac snRNP; U4atac/U6atac x U5 tri-snRNP complex; U6 snRNP; U6atac snRNP
Genetic constraint (gnomAD): Loss-of-function variants: 13 observed, 11.61 expected, observed/expected ratio (o/e) 1.12, 90% interval 0.73 to 1.73. The synonymous counts are far from expectation, so gnomAD's model fits this gene poorly and the ratio says little. Missense variants: 108 observed, 107.37 expected, observed/expected ratio (o/e) 1.01, 90% interval 0.86 to 1.18. Synonymous variants: 70 observed, 44.78 expected, observed/expected ratio (o/e) 1.56, 90% interval 1.29 to 1.87.
Homologues: Orthologues: chimpanzee LSM7 (100% identical), guinea pig LSM7 (100% identical), macaque LSM7 (98% identical), pig LSM7 (98% identical), dog LSM7 (97% identical), mouse Lsm7 (97% identical), rat Lsm7 (96% identical), tropical clawed frog lsm7 (95% identical), zebrafish lsm7 (95% identical), Drosophila melanogaster LSm7 (73% identical), Caenorhabditis elegans lsm-7 (55% identical). Paralogues in human: SNRPG (30% identical).
Diseases named in the same sentence as LSM7 in open-access papers:
LSM7 is named in the same sentence as 15 diseases in open-access papers, as found by Europe PMC text mining. Sharing a sentence is not in itself a finding about the gene and the disease. The quoted sentences say what the papers report.
breast carcinoma (2 papers, 2021 to 2022). "A previous study has shown that LSM7 is significantly associated with T cell responses in breast cancer." (PMID 36389112, 2022).
lung carcinoma (2 papers, 2021 to 2022). "It is found that 3 of the 10 SFs are reported to be connected with lung cancer, namely LSM7, C1QBP, and THOC1." (PMID 35126467, 2021).
Parkinson’s (2 papers, 2023 to 2024). "Dementia-related genes ARHGAP27, CYP1B1, KANSL1, KRTCAP2, LSM7, and GBA are also linked to altered behavior, neurodegeneration, inflammation, and Parkinson’s." (PMID 37588516, 2023). "Specific common coding variants in SPNS1 and MLX may be involved in Parkinson’s disease, and burden tests of rare variants further support that CNIP3, LSM7, NUCKS1 and the polyol/inositol phosphate biosynthetic pathway are associated with the disease." (PMID 37804111, 2024).
thyroid nodule (1 paper, 2022). A small circumscribed mass in the THYROID GLAND that can be of neoplastic growth or non-neoplastic abnormality. "LSM7 overexpression is highly accurate in the preoperative diagnosis of thyroid nodules." (PMID 36371223, 2022).
cancer (4 papers, 2012 to 2022). A tumor composed of atypical neoplastic, often pleomorphic cells that invade other tissues. "Further studies are also required to elucidate the role of Lsm7 in SG formation in mammalian cells, especially when it comes to the mechanisms underlying SG-induced drug resistance or the relationship between SGs and age-related diseases such as cancer and neurodegeneration." (PMID 35764627, 2022). "Furthermore, LSM7 was associated with “regulation of actin cytoskeleton nucleation and polymerization by Rho GTPase”, a pathway that plays an important role in the movement of cancer cells in living tumor tissues." (PMID 34638387, 2021). "The initial category, containing ANKHD1, ATXN8OS, HSPB8, LSM7, MAFB, and TCTN2, is involved in the direct regulation of cancer cell proliferation, apoptosis, and cancerization." (PMID 34235216, 2021). "KIT, CDH1, LSM7, C21orf4, DDI2 mRNA expression levels were significantly different between benign and malignant tumors, p(KIT) < 0.0001; p(CDH1) = 0.004; p(LSM7) = 0.03; p(C21orf4) = 0.01; p(DDI2) = 0.0001." (PMID 22958914, 2012). "Meanwhile, we found that LSM7 and LSM14B proteins were not significantly differentially expressed between normal and cancer tissues." (PMID 34638387, 2021).
LSM7 also shares sentences with these, for which no sentence is quoted: tumor (2 papers); adenoid cystic carcinoma (1); colon cancer (1); dementia (1); endometrial cancer (1); esophageal carcinoma (1); lung adenocarcinoma (1); Lynch syndrome (1); stomach adenocarcinoma (1); uterine corpus endometrial carcinoma (1).